NAT10 (N-acetyltransferase 10)
Diseases named in the same sentence as NAT10 in open-access papers (continued):
Sharing a sentence is not in itself a finding about the gene and the disease.
colorectal cancer (36 papers, 2017 to 2026). A primary or metastatic malignant neoplasm that affects the colon or rectum. "This study presents the sono‐sensitive nanorobot Sono@NAT10, which targets NAT10 condensates to reprogram tumor‐associated macrophages in colorectal cancer." (PMID 41144699, 2026). "High expression of NAT10 in hepatocellular carcinoma and colorectal cancer is associated with a worse prognosis in patients." (PMID 34362389, 2021). "In addition, membranous NAT10 positivity has been detected in the aggressive pretumor area of invasive nests in colorectal cancer, and its expression is linked to aggressive clinical behavior in this cancer type." (PMID 41316475, 2025). "Despite overexpression of N-acetyltransferase 10 (NAT10) in colorectal cancer (CRC), its immunomodulatory role in the tumor microenvironment remains elusive." (PMID 41542770, 2026). "Through inhibiting NAT10 expression, miR-6716-5p downregulated E-cadherin levels and promoted colorectal cancer cells migration and invasion." (PMID 40588654, 2025). "In colorectal cancer, NAT10 facilitates disease progression through the NAT10/KIF23/GSK-3β/β-catenin axis." (PMID 41316475, 2025). "In colorectal cancer, NAT10 mediates the stability of KIF23 mRNA by binding to its mRNA 3'UTR region and up-regulating its mRNA ac4c modification." (PMID 40588654, 2025). "NAT10‐mediated N4‐acetylation of ferroptosis suppressor protein FSP1 mRNA to promote the progression of colorectal cancer." (PMID 39640362, 2024). "In colorectal cancer cells, NAT10 was found to enhance the stability of KIF23 mRNA by up-regulating its ac4C modification." (PMID 38459019, 2024). "Using public databases and in vitro experiments, we verified the expression and biological function of NAT10, as the key RNA acetylation modification enzyme, in colorectal cancer." (PMID 36908042, 2023). "According to the Human Protein Atlas database, 8 out of 10 colorectal cancer samples were positive for NAT10 in immunohistochemical staining, while normal colon samples were all negative for NAT10 expression." (PMID 36908042, 2023). "The results showed that NAT10 was highly expressed in colorectal cancer, and significantly promoted colorectal cancer cell proliferation." (PMID 36908042, 2023). "Using bioinformatics algorithms and in vitro experiments, we found that NAT10 promotes the development of colorectal cancer." (PMID 36908042, 2023). "NAT10 is involved in the development of colorectal cancer possibly by regulating immune infiltration." (PMID 36908042, 2023). "In previous studies, the genomic depletion or chemical inhibition of NAT10 was confirmed to decrease the growth, cell cycle progression and BrdU incorporation of colorectal cancer cells." (PMID 35743017, 2022). "Previous studies have shown that using CRISPR/Cas9 technology to completely knock out NAT10 in colorectal cancer cells can lead to cell death, demonstrating that NAT10 is essential for the proliferation of colorectal cancer cells." (PMID 35743017, 2022). "According to pan-cancer analysis of NAT10, the partner of THUMPD1 for mRNA acetylation, high NAT10 expression is associated with worse survival in LIHC, lymphoma and colorectal cancer." (PMID 34762107, 2021). "N-acetyltransferase 10 (NAT10) is a protein that was determined to be important in colorectal cancers." (PMID 32365809, 2020). "Several reports have shown that the overexpression of NAT10 promotes cancer growth and metastasis and results in worse outcomes in patients with the liver and colorectal cancers." (PMID 28880216, 2017).
colorectal cancer (continued). "Similar to these results, NAT10 leads to enhanced transcription and increased expression of PD-L1 by promoting the acetylation of nucleophosmin 1 in different cancer cells, including human breast cancer, melanoma, and colorectal cancer cells." (PMID 40245789, 2025). "NAT10, an acetyltransferase involved in regulating ac4C formation, is related to the pathogenesis of numerous conditions, including subtypes of ovarian cancer (OC) with poor prognosis and highly aggressive colorectal cancer (CRC)." (PMID 41316475, 2025). "In colorectal cancer, NAT10 facilitates the formation of micronuclei (MN) during DNA replication." (PMID 40881352, 2025). "Similarly, enhancing NAT10 expression has been revealed to suppress the metastasis of colorectal cancer cells." (PMID 41316475, 2025). "In liver cancer and colorectal cancer, NAT10 has been found to induce cancer cell proliferation." (PMID 41316475, 2025). "Conversely, miR-6716-5p binds specifically to the 3' UTR of NAT10 mRNA, leading to reduced levels of NAT10 mRNA and downregulation of NAT10 expression, eventually suppressing colorectal cancer metastasis, which seems to contradict the earlier identified role of NAT10 in promoting cancer growth." (PMID 41316475, 2025). "Furthermore, in colorectal cancer, the N-acetyltransferase NAT10 inhibits ferroptosis by N4-acetylating FSP1 mRNA to increase its mRNA stability and improve its translational efficiency." (PMID 39881208, 2025). "NAT10 mediates KIF23 acetylation to promote colorectal cancer progression." (PMID 39640362, 2024). "In colorectal cancer, NAT10 facilitates tumor progression by ac4C modification of KIF23 mRNA." (PMID 38243170, 2024). "NAT10 expression positively correlated with immune infiltration in colorectal cancer." (PMID 36908042, 2023). "We also measured the expression level of NAT10 in the colorectal cancer tissue samples." (PMID 36908042, 2023). "Therefore, we analysed the relationship between the expression of NAT10 and four mismatch repair proteins in colorectal cancer patients." (PMID 36908042, 2023). "We investigated the biological function of NAT10 in colorectal cancer." (PMID 36908042, 2023). "However, the roles of both ac4C and its ‘writer’ protein N-acetyltransferase 10 (NAT10) played in the disease especially colorectal cancer (CRC) are unclear." (PMID 36522719, 2022). "In addition, high NAT10 expression was found to be related to poor survival in human hepatocellular carcinoma, acute myeloid leukemia and to promote colorectal cancer progression by increasing micronuclei." (PMID 34094911, 2021). "Under oxidative stress condition, NAT10 could be stimulated and promote MN formation by accelerating DNA replication and DNA damage in colorectal cancer, indicating that NAT10 not only participates in DNA damage repair but also potentially contributes to its initiation phase." (PMID 40588654, 2025). "Additionally, NAT10 could increase the expression of KIF23 by up-regulating ac4C modification of KIF23 3′-UTR in colorectal cancer." (PMID 38182571, 2024). "Based on our findings, NAT10 may be a new target for colorectal cancer treatment." (PMID 36908042, 2023). "In addition, several studies have shown that overexpression of NAT10 could promote tumor progression in cancers including colorectal cancer, epithelial ovarian cancer, and melanoma." (PMID 34094911, 2021). "Moreover, NAT10 is downregulated in human colorectal cancer." (PMID 28859621, 2017). "This study introduces the Sono@NAT10 nanorobot for colorectal cancer (CRC) immunotherapy, designed to target NAT10 condensates in macrophages." (PMID 41144699, 2026).
colorectal cancer (continued). "Previous researches have shown that NAT10 inhibits ferroptosis by stabilizing the mRNA of ferroptosis suppressor protein 1 (FSP1) through ac4C modification, promoting the progression of colorectal cancer." (PMID 40303290, 2025). "Additionally, since 5-fluorouracil (5-Fu) promotes the ubiquitin-mediated degradation of NAT10, a triple combination of 5-Fu, Remodelin, and cetuximab has been shown to be effective in KRAS wild-type colorectal cancer." (PMID 41316475, 2025). "However, the role of mRNA acetylation modification levels and the NAT10 gene in colorectal cancer and their effect on immunotherapy were not investigated." (PMID 36908042, 2023).
breast cancer (32 papers, 2021 to 2026). A primary or metastatic malignant neoplasm involving the breast. "In malignancies such as hepatocellular carcinoma, colorectal cancer, and breast cancer, abnormal expression of NAT10 has been associated with tumor progression by promoting cell proliferation, migration, and invasion." (PMID 41310903, 2025). "Loss of NAT10 decreases lung metastases in genetically modified and allograft mouse models of breast cancer." (PMID 39949372, 2025). "Notably, all the FA metabolic genes ELOVL6, ACSL1, ACSL3, ACSL4, ACDSB and ACAT1 showed significant positive correlation with NAT10 suggesting that overexpression of NAT10 in breast cancer patients is associated with FA metabolism." (PMID 36149760, 2022). "first showed that NAT10 was associated with cancer by demonstrating that it could significantly promote cell growth in epithelial ovarian cancer and breast cancer." (PMID 34094911, 2021). "Targeting NAT10 represents a promising therapeutic strategy to overcome immunosuppression and improve patient outcomes in breast cancer." (PMID 41501889, 2026). "Together, our data indicate that NAT10 is a driver of breast cancer and lung cancer metastases to multiple organs." (PMID 40138393, 2025). "Pharmacological evaluations in breast cancer and hepatocellular carcinoma models demonstrate that NAT10 silencing effectively counteracts doxorubicin-induced EMT, thereby reversing drug-resistant phenotypes in tumor cells." (PMID 40881352, 2025). "demonstrate that siRNA targeting NAT10 or Remodelin can significantly reverse doxorubicin resistance in breast cancer cell lines, indicating that NAT10 plays a role in the development of doxorubicin resistance." (PMID 39764566, 2025). "Our functional studies suggest the RNA acetyltransferase function of NAT10 is less important for breast cancer cell proliferation in vitro." (PMID 40138393, 2025). "Afterward, we used a stable sh-NAT10 cell line to explore the role of NAT10 in regulating the sensitivity of breast cancer cells to olaparib." (PMID 40606759, 2025). "We next sought to examine which molecular function of NAT10 is required for breast cancer cell growth." (PMID 40138393, 2025). "Among all main metastasis sites of breast cancer, brain metastases exhibited the highest levels of NAT10, PHGDH, and PSAT1, followed by liver metastases." (PMID 40138393, 2025). "In breast cancer, NAT10-mediated stabilization of JunB mRNA upregulates LDHA expression, creating an immunosuppressive niche via lactate-driven inhibition of cytotoxic T cells." (PMID 40588654, 2025). "In breast cancer, NAT10 overexpression mediates acetylation modifications of PARP1 to regulate its protein homeostasis." (PMID 40881352, 2025). "In breast cancer cells with NAT10 knockdown or KO, ac4C levels decrease, leading to the downregulation of several key ferroptosis genes, including SLC7A11, GCLC, MAP1LC3A, and SLC39A8143." (PMID 39764566, 2025). "In breast cancer cells, NAT10 knockdown reversed docetaxel‐induced EMT and restored sensitivity to docetaxel, as evidenced by upregulated CDH1 (E‐cadherin) expression and downregulated VIM (vimentin) expression." (PMID 39764566, 2025). "Silencing PHGDH or PSAT1 in metastatic breast cancer cells inhibits their growth in the serine/glycine-limited condition, phenocopying the effects of NAT10 depletion." (PMID 40138393, 2025). "In breast cancer, NAT10 knockout significantly downregulates ferroptosis-essential genes (SLC7A11, GCLC, MAP1LC3A, and SLC39A8)." (PMID 40881352, 2025). "NAT10 promotes cell proliferation in breast cancer by acetylating CEP170 mRNA to increase its translation efficiency." (PMID 41310903, 2025). "To dissect the functions of NAT10 in breast cancer, we generated two independent NAT10 inducible knockdown 231-BrM3 cell lines and demonstrated that knockdown of NAT10 significantly decreased the clonogenic ability of 231-BrM3." (PMID 40138393, 2025).
breast cancer (continued). "As a highly lethal cancer type, breast cancer has been found to exhibit abnormally high NAT10 expression." (PMID 39764566, 2025). "A recent study showed that inhibiting NAT10 expression suppresses the proliferation and invasion of breast cancer cells." (PMID 39764566, 2025). "To date, Remodelin has shown significant preclinical therapeutic efficacy in models of liver cancer, breast cancer, melanoma, and leukemia, primarily through NAT10 inhibition." (PMID 39764566, 2025). "We also show that breast cancer cell growth and NAT10 downstream genes PHGDH and PSAT1 are regulated by NAT10 in an RNA helicase activity–dependent manner." (PMID 40138393, 2025). "Inhibition of NAT10 reverses doxorubicin resistance in breast cancer by reversing the activation of EMT." (PMID 39640362, 2024). "A positive correlation between PD-L1 and NAT10 expression was found in both breast cancer and lung adenocarcinoma." (PMID 38243170, 2024). "NAT10 also confers resistance to DNA-damaging chemotherapy and radiotherapy in breast cancer cells via MORC2 acetylation." (PMID 36609449, 2023). "In breast cancer, NAT10-mediated acetylation of MORC2 regulates cell cycle checkpoint control and resistance to DNA-damaging chemotherapy and radiotherapy." (PMID 36765042, 2023). "Knockdown of NAT10 was also performed and confirmed in other breast cancer cell lines, that is, MDA‐MB‐231, MDA‐MB‐468, and T47D." (PMID 36149760, 2022). "The comparison revealed that NAT10 expression was significantly higher in all PAM50 subtypes of breast cancer compared to paraneoplastic tissues." (PMID 36553667, 2022). "The expression levels of the studied genes were also downregulated in breast cancer cell lines 48 h posttreatment with Remodelin (the only known inhibitor of NAT10)." (PMID 36149760, 2022). "We used the MDA-231 and BT-549 as well as MCF-7 cells, another classis type of breast cancer cell line, for analysis of spontaneous MN formation by immunofluorescent staining of Lamin B1 and NAT10." (PMID 34123836, 2021). "Moreover, the use of NAT10 inhibitors has demonstrated the restoration of sensitivity in capecitabine-resistant breast cancer cells to chemotherapy, both in vitro and in vivo." (PMID 39969189, 2025). "The effect of NAT10 loss on MDA-MB-157 and 231-BrM3 is stronger than that on T47D, suggesting that TNBC cells may be more dependent on NAT10 than ER-positive breast cancer cells." (PMID 40138393, 2025). "Notably, in breast cancer (BC), NAT10, through its role as a lncRNA (CD2BP2-DT), promotes tumor progression." (PMID 41316475, 2025). "S3, I and J), we asked whether NAT10 affects breast cancer metastasis to other organs such as the bone and lungs." (PMID 40138393, 2025). "Additionally, the inhibition of NAT10 sensitizes capecitabine-resistant breast cancer cells to chemotherapy both in vitro and in vivo." (PMID 40606759, 2025). "We further asked whether NAT10-regulated cell proliferation is a general phenomenon in other breast cancer subtypes and MDA-MB-231 derivatives with distinct organotropism." (PMID 40138393, 2025). "The expression levels of NAT10 protein in breast cancer, ovarian cancer, colon cancer, renal clear cell carcinoma, endometrial carcinoma, lung cancer, head and neck squamous cell carcinoma, pancreatic cancer, glioblastoma and liver cancer were greatly higher compared to those in normal tissues." (PMID 38308713, 2024). "The expression levels of NAT10 in breast cancer were annotated based on sequencing reads of NAT10." (PMID 36553667, 2022). "However, whether NAT10 can regulate DNA damage repair (DDR) in breast cancer by catalyzing the acetylation of RNA molecules remains to be further explored." (PMID 40606759, 2025). "Notably, radiation has been shown to enhance NAT10-mediated acetylation of MORC2 in breast cancer, suggesting that NAT10 may serve as a potential therapeutic target to overcome RT resistance." (PMID 40109769, 2025).